CTLA4 (cytotoxic T-lymphocyte associated protein 4)
Diseases named in the same sentence as CTLA4 in open-access papers (continued):
Sharing a sentence is not in itself a finding about the gene and the disease.
melanoma (continued). "This outcome is supported by similar observations made in anti-PD-L1/CTLA-4-resistant melanoma and warrants the investigation into combinatorial treatment with the inhibitors of the PI3K and JAK/STAT pathway or VEGFR." (PMID 35327375, 2022). "We conclude that GNP-LLO91–99 nanovaccines can work as monotherapies or combinatory immunotherapies with anti-CTLA-4 or anti-PD-1 antibodies for solid tumors with high T cell infiltration, such as bladder cancer or melanoma." (PMID 35626016, 2022). "A series of clinical trials later demonstrated that inhibition of CTLA4 or PD-1 led to desirable responses and improved overall survival in patients with various cancers including melanoma and squamous-cell non-small-cell lung cancer." (PMID 35372044, 2022). "Both Ctla4+/− Pdcd1−/− and melanoma models were used to assess treatment options (CTLA4-IgG1 and anti-TNFα, respectively) paving the way for a more comprehensive search for novel and more specific therapeutic options." (PMID 35455289, 2022). "Melanoma patients were more likely to receive CTLA-4 inhibitors compared to other cancers (65.8%, p < 0.001)." (PMID 35960456, 2022). "Noteworthily, immunotherapy blocking PD-1, PD-L1, and CTLA4 is extensively employed for the treatment of various cancers, especially melanoma." (PMID 36034849, 2022). "Ipilimumab, as the most widely used anti-CTLA4 antibody, has been applied to the treatment of advanced melanoma since the 2000s." (PMID 35493449, 2022). "When viewed in combination, these studies demonstrated an essential role of CHI3L1 in melanoma inhibition of T cell co-stimulation and the induction of CTLA-4 and its ligands." (PMID 36618349, 2022). "High ratio of Teff/Treg and Teff/MDSC are found in the tumor of melanoma-bearing mice treated with combination blockade of PD-1 and CTLA-4." (PMID 34875483, 2022). "Two cohort studies used PD1 to treat melanoma, two cohort studies used CTLA4 to treat melanoma, one cohort study combined PD1 with CTLA4 to treat melanoma, and one cohort study used PD1 to treat gastric cancer." (PMID 35141160, 2022). "Since its approval by the FDA in 2011 for the treatment of advanced melanoma, CTLA-4 inhibitor ipilimumab has gained space in other solid tumors therapy." (PMID 36844955, 2022). "CTLA-4 inhibits the activation of T cells and PD-1 binds to PD-L1/PD-L2 ligands that are expressed in melanoma, thus inhibiting immune attack." (PMID 36135194, 2022). "The clinical trial data showing superior anti-melanoma effects of ICIs such as pembrolizumab (anti-PD-1), nivolumab (anti-PD-L1), and ipilimumab (anti-CTLA-4), over traditional therapies, has led to their rapid FDA approval." (PMID 35515106, 2022). "In 2011, FDA approved the first ICB therapy: Ipilimumab, an anti-CTLA-4 drug, designated for melanoma metastatic treatment." (PMID 36033972, 2022). "The infiltration of CD68+CD16+ classically activated M1 macrophages was higher in melanoma tumors that responded to anti-CTLA-4." (PMID 36435510, 2022). "At the same time, IFN-γ levels increased in melanoma tissues of mice treated with CD73 antibody in combination with CTLA-4 antibody." (PMID 36159861, 2022). "We therefore combined APR-246 with anti–PD-1 (RMP1-14) and anti–CTLA-4 (9D9) in B16-melanoma-bearing mice and found a significantly longer survival compared with dual ICB alone (P < 0.001)." (PMID 36106631, 2022). "VLD occurs in 4.7–37.5% of the melanoma patients undergoing anti-PD1 treatment and in 2.9–4.9% of the melanoma patients treated with CTLA-4-antibodies." (PMID 36230498, 2022). "In earlier 2011, the US Food and Drug Administration approved anti-CTLA-4 for the treatment of advanced stage melanoma." (PMID 35903691, 2022). "Overall survival and progression free survival reported among the studies for melanoma patients and for melanoma V600K patients treated with BRAFi ± MEKi and/or immunotherapy (anti-PD/L-1 and/or anti-CTLA-4)." (PMID 35160279, 2022).
melanoma (continued). "SRS was tolerated in patients with melanoma brain metastases treated with either anti-PD-1 or anti-CTLA-4 ICB therapy, with greater reductions in lesion volume for patients treated with ICB therapy and SRS." (PMID 35440655, 2022). "ICIs, such as those targeting the PD-1/PDL-1 or CTLA-4 interactions, have shown a high degree of clinical efficacy as single agent therapies in non-small cell lung cancer and melanoma, and the list of cancer subtypes under investigation is rapidly expanding." (PMID 36140319, 2022). "The CTLA-4 checkpoint inhibitor system and its roles in autophagy and cancer immunity have been mostly evaluated in melanoma." (PMID 36295867, 2022). "Ipilimumab is a monoclonal antibody (mAb) targeting cytotoxic T-lymphocyte associated protein (CTLA-4), demonstrating increased lymphocyte counts and CD4+/CD8+ T cell percentages in melanoma patients correlated to improved survival." (PMID 35345849, 2022). "In melanoma tumors that responded to anti-CTLA-4, increased numbers of several subsets of CD4+Th1 cells have been observed." (PMID 36435510, 2022). "Antibodies that disrupt the immunological checkpoint CTLA-4 and PD-1/PD-L1) pathways for the treatment of melanoma were approved by the FDA in 2011 and 2014, respectively." (PMID 35744922, 2022). "The Dutch Melanoma Treatment Registry included 1,250 patients of which 65 received TNFi for irAEs related to PD-1 and/or CTLA-4 inhibitors." (PMID 36081549, 2022). "Among them, anti-CTLA-4 (i.e., ipilimumab) was the first-in-class to be approved against melanoma in 2011." (PMID 36365144, 2022). "One case series of 22 patients treated with tocilizumab (two of whom started treatment prior to receiving ICI) demonstrated a good safety profile and efficacy for the treatment of irAEs in melanoma (related to PD-1, PD-L1, and/or CTLA-4 inhibitors)." (PMID 36081549, 2022). "For example, the PI3Kb inhibitor GSK2636771 sensitized PTEN-null melanomas to both CTLA-4 and PD-1 inhibitors and promoted T-cell infiltration to enhance the antitumor activity in vivo." (PMID 36189283, 2022). "Immune checkpoint inhibitors (ICI), such as anti-PD1, anti-PDL1, and anti-CTLA4 antibodies lead to reactivation of immune pathways, promoting rejection of melanoma." (PMID 36248850, 2022). "Autoantibodies were reported to become detectable in 19.2% of melanoma patients after treatment with anti-CTLA-4 antibody." (PMID 35159059, 2022). "Using the TIDE datasets, we also found that in melanoma patients who received the PD-L1 and CTLA4 treatments, high IEGPI-score patients had a better OS and RFS." (PMID 36147906, 2022). "Patients with melanoma who switched from combination anti-PD-1 and anti-CTLA-4 to anti-PD-1 monotherapy reported overall irAE rates of 50%, with 18% grade ≥ 3 and 18% having the same irAE." (PMID 35876957, 2022). "Previous studies have identified immunotherapeutic targets, including PD1, PDL1 and CTLA4, that promote the treatment of non-small-cell lung cancer, melanoma and renal carcinoma." (PMID 35562760, 2022). "The patient’s melanoma was BRAF V600E mutated, and he had received multiple prior treatments including PD-1 inhibitors, CTLA-4 inhibitor, as well as BRAF/MEK inhibitor combination therapy." (PMID 36104795, 2022). "In both anti-PD-L1 immunotherapy of BLCA and anti-CTLA-4 immunotherapy of melanoma, high expression of FASN predicted a poor prognosis." (PMID 36555243, 2022). "A recent study in patients with melanoma treated with combined immune checkpoint blockade (CICB) targeting CTLA-4 and PD-1 who developed ≥ grade 3 colitis demonstrates an intestinal overexpression of IL1β and TNF compared to normal tissue." (PMID 35432346, 2022). "A prospective randomized clinical trial (NCT04988841) assessing the tolerance and clinical benefit of MaaT013 (administered via enema) in melanoma patients treated with CTLA-4 and PD1 inhibitors has begun." (PMID 36588712, 2022).
melanoma (continued). "The authors performed a longitudinal multi-omics analysis on a large cohort of melanoma patients, either naïve or previously treated with anti-CTLA-4, revealing how tumor co-evolves with the antitumoral immune response during anti-PD-1 treatment." (PMID 36550555, 2022). "In some melanoma patients, CTLA-4 inhibition has been found to elicit an increase in the frequency of LAG3+ TILs." (PMID 35434132, 2022). "The AUC curve of DLAT was 0.54 in Miao Kidney (ICB) data, while the scores achieved 1.00 in Zhao glioblastoma (PD-1) and 0.80 in Nathanson melanoma (CTLA4)." (PMID 36581992, 2022). "Worth specific mentioning are two clinical studies of T-VEC with either anti-PD-1 or anti-CTLA-4 antibodies, achieving dramatically improved clinical responses with up to ~ 67% objective response rate in patients with advanced melanoma." (PMID 36221123, 2022). "According to a recent retrospective study, melanoma patients responding to anti-PD-1 or anti-CTLA-4 therapy exhibited low TCR diversity, in pre-treatment peripheral T cells." (PMID 36550555, 2022). "EZH2 inhibition can cooperate with anti-CTLA-4 and IL-2 immunotherapy to inhibit the growth of melanoma." (PMID 35907846, 2022). "We have observed a cooperative therapeutic interaction of low dose 90Y delivered with NM600 and anti-PD-L1 and anti-CTLA-4 in syngeneic murine B78 melanoma models." (PMID 36678756, 2022). "In order to check if it is possible to counteract this process, an interesting experiment has been conducted on a mice melanoma model: anti-CTLA-4 antibodies have been administered together with an IDO enzyme inhibitor (1-metylotryptophan, 1MT)." (PMID 35269988, 2022). "In sum, we observed a relatively high rate of hepatitis incidence in the first 100 days after anti-PD-1 & CTLA-4 treatment initiation for advanced melanoma." (PMID 36503532, 2022). "Anti-CTLA-4 inhibitors were validated to boost HLA binding affinity of TIL T cells in melanoma as well as promoting CD8+ TILs expansion in Lewis lung carcinoma." (PMID 35433427, 2022). "Human antibodies targeting CTLA-4 (cytotoxic T lymphocyte antigen-4) have displayed significant anticancer potential against multiple melanomas and tumor types." (PMID 35337133, 2022). "Chronic exposure to tumor antigens and the overexpression of CTLA-4 and PD-L1 on melanoma cells raise the inhibitory receptors on T cells, which hinder their activation." (PMID 36003368, 2022). "In melanoma, the efficacy of anti-CTLA-4 therapy can be enhanced by targeting various immunosuppressive mechanisms in tumor tissues, including CD73." (PMID 36159861, 2022). "In the case of the triple wild-type melanoma, the only recommended therapy option is immunotherapy in the form of anti-PD-1 (programmed cell death protein 1) and/or anti-CTLA-4 (cytotoxic T cell antigen 4) antibodies." (PMID 35628196, 2022). "Currently approved mAbs for melanoma enhance T cell effector immune responses by blocking immune checkpoint molecules PD-L1/PD-1 and CTLA-4." (PMID 36211808, 2022). "As expected, melanoma patients with high TIIClnc signature scores tended to respond to anti-CTLA-4 immunotherapy." (PMID 35966587, 2022). "When applied in combination with the CTLA-4 inhibitor Ipilimumab and anti-PD-1 mAbs, it produced more effective inhibition of melanoma growth compared to the ICI alone." (PMID 35954441, 2022). "RIG-I in combination with CTLA-4 checkpoint inhibitors have been used to treat experimental melanoma in mice." (PMID 35998812, 2022). "Melanoma treatment has recently made headway with the advent of immunotherapies (anti-CTLA4 and anti-PD-1 antibodies)." (PMID 36341357, 2022). "Studies to undertaken to evaluate the effects of FRGxCTLA-4 to FRG and anti-CTLA-4 alone and in combination, in in vivo animal model of melanoma lung metastasis and in vitro cocultures composed of activated T cells and A357 human melanoma cells." (PMID 36618349, 2022).
melanoma (continued). "At the time of symptomatic infection, this patient received a systemic treatment with CTLA-4+PD-1 for advanced melanoma." (PMID 36091146, 2022). "Patients with melanoma treated with anti-CTLA-4, and with high Faecalibacterium abundance and low abundance of Bacteroidales, had significantly prolonged PFS compared to those with low and high abundance of these bacteria (p = 0.03 and p = 0.05)." (PMID 36428677, 2022). "Recently, combining anti-CTLA-4 treatment with DNMTi in melanoma has given promising results in terms of anti-tumor activity and improvement in immune activation." (PMID 35887150, 2022). "CTLA-4 ICB increased the frequencies of gp100- or NY-ESO-1-specific CD8+ T cells in melanoma patients after vaccination against the respective antigens." (PMID 35651800, 2022). "Typical immune checkpoint molecules such as CTLA-4 and PD-1/PD-L1 are related to the progress and prognosis of malignant melanoma." (PMID 35326741, 2022). "In 2014, TMB was first confirmed to correlate with the efficacy of the CTLA-4 antibody in the treatment of malignant melanoma." (PMID 35935979, 2022). "There have been multiple studies that showed antitumor response by CTLA-4 blockade in animal models of breast, prostate, lymphoma, colon, and melanoma malignancies." (PMID 36648843, 2022). "An analogous response was observed for anti-CTLA-4 antibody in mice with melanoma, sarcoma and colorectal cancer." (PMID 36428677, 2022). "In melanoma patients resistant to anti-PD-1+ anti-CTLA-4 immunotherapy, OXPHOS-related genes are upregulated." (PMID 36612059, 2022). "The initial studies mainly investigated the clinical efficacy and safety of anti-PD1/PDL1 therapy for non-specific cancer, and subsequently compared anti-PD1/PDL1 therapy with anti-CTLA4 antibodies and targeted therapies for melanoma." (PMID 35493449, 2022). "Checkpoint blockade treatments, such as anti-PD-1 and anti-CTLA-4 have shown impressive success in the treatment of several malignancies such as melanoma and non-small cell lung cancer (NSCLC)." (PMID 35223381, 2022). "Ipilimumab (Yervoy) is a human IgG1 mAb that can inhibit the function of CTLA-4 and was first approved and recommended for the treatment of melanoma in 2011." (PMID 35621637, 2022). "Minimal change disease was described in one patient receiving the anti-PD-1 antibody pembrolizumab for Hodgkin lymphoma and two patients receiving the CTLA-4 antibody ipilimumab for melanoma, respectively." (PMID 37674988, 2022). "CTLA-4 inhibitor and PD-1 inhibitor (PD-1/PD-L1 inhibitor) have strong antitumour activities in different tumours including melanoma, non-small-cell lung cancer and kidney cancer." (PMID 36118669, 2022). "The first drug to be approved by the US Food and Drug Administration (FDA) for tumor immunotherapy is ipilimumab, an anticytotoxic T lymphocyte antigen-4 (CTLA-4) antibody, which is used to treat melanoma." (PMID 35528539, 2022). "SubMap was used to compare the prediction response to anti-PD1 and anti-CTLA4 therapy results with another dataset containing 47 patients with melanoma that responded to immunotherapies." (PMID 36727078, 2022). "For example, a case series of 3 patients with melanoma refractory to nivolumab (anti-PD-1) responded to ipilimumab (anti-CTLA-4) combined with radiotherapy." (PMID 36289601, 2022). "When CTLA-4 blockade is combined with melanoma cell vaccine, the ratio of effector T cells (Teff)/Treg induced in tumor is larger, which is directly associated with tumor rejection." (PMID 34875483, 2022). "Similar to PD-L2, the methylation status of CTLA-4 is also inversely correlated with its mRNA level in melanoma tissue." (PMID 35693795, 2022). "Immune checkpoint inhibitors (ICI) have shown clinical activity in advanced melanoma with significant survival benefits and response rates of 19% for the anti-CTLA-4 antibody ipilimumab and 36–44% for the anti-PD-1 antibodies nivolumab and pembrolizumab." (PMID 36678712, 2022).
melanoma (continued). "In vitro studies substantiated that diclofenac enhanced the killing of melanoma cells by T cells induced by anti-PD-1 and anti-CTLA-4 monoclonal antibodies." (PMID 36620597, 2022). "ICB therapy targeting CTLA-4, PD-1, and PD-L1 had shown significant therapeutic benefit and become an attractive treatment option for several malignant cancers, such as melanoma, bladder cancer, and lung cancer." (PMID 35516457, 2022). "While earlier studies have shown that PD-L1 and CTLA-4 blockade have therapeutic benefit in some cancers including melanoma and Hodgkins diseases, other cancers such as CRC except for a small subset of tumors are non-responsive." (PMID 35692780, 2022). "Indeed, expanded clones in tumours exhibiting a high TMB, such as melanoma, may be recognising tumour-derived peptides, but they might be inhibited by programmed cell death protein 1 (PD-1), or cytotoxic T-lymphocyte-associated protein 4 (CTLA-4)." (PMID 35406543, 2022). "Immune checkpoint inhibitor PD-1/PD-L1/CTLA-4 has conducted extensive research on some tumors such as melanoma." (PMID 36147250, 2022). "Downregulation of CTLA-4 allows for the expansion of naturally developed melanoma-specific cytotoxic T cells." (PMID 35945708, 2022). "In recent years, checkpoint blockade of the CTLA-4 or PD-1/PD-L1 axis has been proven to be an effective strategy for advanced melanoma, non-small-cell lung carcinoma, advanced renal cell carcinoma and Hodgkin lymphoma." (PMID 35000592, 2022). "CTLA-4 and PD-L1 blockers have been investigated in several trials of melanoma, non-small-cell lung cancer, breast cancer, colorectal cancer, etc.." (PMID 36341387, 2022). "The successful application of ICG-inhibitors (ICI) such as anti-CTLA-4 and anti-PD-1/PD-L1 in melanoma, lung cancer, and other cancers makes immunotherapy a feasible treatment for patients with advanced cancer." (PMID 36467461, 2022). "Recent studies focus on combining PD1/PD-L1 antibodies with anti-CTLA-4 inhibitors to target various cancers, including melanoma." (PMID 35954441, 2022). "In this study, circulating B cells were analyzed in 39 advanced melanoma patients before and after first cycle of treatment with anti PD-1, anti-CTLA4 or combination therapy." (PMID 36713389, 2022). "Selective anti-PD-L1, anti-PD-1, and/or anti-CTLA-4 mAbs have brought about a revolution in treatment of many types of cancer, among which lung cancer and melanoma have seen the greatest clinical efficacy." (PMID 35145371, 2022). "So far, two anti-PD-1 antibodies (pembrolizumab and nivolumab) and one anti-CTLA-4 antibody (ipilimumab) have been approved for melanoma treatment." (PMID 35158770, 2022). "Blocking CTLA-4 and PD-1 can improve the prognosis of some cancers, including melanoma, non-small cell lung cancer, and renal cell carcinoma." (PMID 36147250, 2022). "The IPS scores of four various subtypes (CTLA4_neg_PD1_neg, CTLA4_pos_PD1_neg, CTLA4_neg_PD1_pos, and CTLA4_pos_PD1_pos) were applied to predict the response of the melanoma patients to anti-CTLA4 and anti-PD1 treatment." (PMID 36034849, 2022). "Combination IO (anti-CTLA4 and anti-PD-1) and TT that inhibit BRAF V600 E/K and MEK (known to be mutated in approximately 40-50% of melanoma patients) are effective at treating MBM and prolonging PFS." (PMID 35600355, 2022). "Because BRAF-mutated tumors also exhibit the overexpression of genes associated with immunosuppression, such as CTLA-4 or PD-L1, immune checkpoint inhibitors, anti-CTLA-4 and anti-PD-1 have also been approved for the treatment of melanoma." (PMID 36009363, 2022). "RIG‐I agonists in combination with immune checkpoint inhibitors anti‐PD‐1 and anti‐CTLA‐4 have proven to be effective as a combined therapy for melanoma and AML." (PMID 35430766, 2022). "This sparked a surge in melanoma immunotherapy research, with antibodies targeting CTLA-4 and PD-1 proven to be very effective." (PMID 35744922, 2022).